P2RX7 (purinergic receptor P2X 7)
Diseases named in the same sentence as P2RX7 in open-access papers (continued):
Sharing a sentence is not in itself a finding about the gene and the disease.
HIV-1 infection (2 papers, 2015 to 2020). The type species of lentivirus and the etiologic agent of acquired immunodeficiency syndrome (AIDS). "P2RX7 and P2YR antagonists have been shown to inhibit HIV-1 infection at potencies similar to those of P2RX1 antagonists, but these compounds do not appear to impact virus-cell membrane fusion." (PMID 32155980, 2020). "The P2RX7 antagonist A740003, which inhibits HIV-1 infection, fails to inhibit virus-membrane fusion as measured by BlaM-Vpr assays." (PMID 32155980, 2020).
liver cancer (2 papers, 2016 to 2021). An epithelial or non-epithelial malignant neoplasm that arises from the liver. "In addition, studies have shown that P2RX7 polymorphisms may affect sputum metabolism and play a critical role in the development of liver cancer." (PMID 33501930, 2021).
liver cirrhosis (2 papers, 2015 to 2025). "Notably, HBV-miR-2 activated genes including inflammatory genes like P2RX7 and PYCARD, fibrosis-induced genes like ANXA2 and MIF oncogenic genes like FOS and JUN, which were further verified via RT-qPCR and highly expressed in the particular stages of CHB, liver cirrhosis and HCC." (PMID 40405227, 2025).
polycystic kidney disease (2 papers, 2013 to 2023). A usually autosomal dominant and less frequently autosomal recessive genetic disorder characterized by the presence of numerous cysts in the kidneys leading to end-stage renal failure. "Other studies have used zebrafish and P2X7 antagonists or p2rx7 gene knockdown techniques to establish a role for P2X7 in disorders such as polycystic kidney disease, seizure, and inflammation during tissue injury." (PMID 37175933, 2023). "CRISPR/Cas9 has been used to globally delete the P2rx7 gene in PCK/CrljCrl-Pkhd1pck/Crl (PCK) rats, derived from Sprague–Dawley rats encoding a mutation in the Pck locus and serving as a model of inherited polycystic kidney disease." (PMID 37175933, 2023).
proteinopathies (2 papers, 2020 to 2021). "Taken together, P2RX7 activation and subsequent inflammatory response represent a common purinergic dysregulation in proteinopathies such as AD, PD and ALS." (PMID 34054698, 2021).
Senile plaques (2 papers, 2019 to 2023). Senile plaques are extracellular deposits of amyloid in the gray matter of the brain. "Using RNAScope we detect P2RX7 mRNA in microglia and astrocytes in human AD brain, including in the vicinity of senile plaques." (PMID 37716378, 2023).
adenoma (1 paper, 2025). A neoplasm arising from the epithelium. "Specifically, GBP2 and P2RX7 were significantly downregulated in both the “Adenomas and Adenocarcinomas” subtype and the “Cystic, Mucinous and Serous Neoplasms” subtype (p < 0.001), while SLC11A1 and HCLS1 were significantly upregulated in these two subtypes (p < 0.01)." (PMID 41007849, 2025).
Anorexia (1 paper, 2020). Lack of desire to eat (loss of appetite). "Next, we blocked purinergic receptor P2RX7 signaling specifically on brain macrophages during PDAC via intracerebroventricular (ICV) injection of oxidized ATP (oATP), which prevented circulating myeloid cell recruitment to the brain and attenuated anorexia." (PMID 32391790, 2020).
Ataxia (1 paper, 2016). Ataxia refers to impaired coordination of voluntary muscle movement. "In P2rx7+/+ mice, PCP induced hyperlocomotion, stereotype behavior, ataxia and social withdrawal." (PMID 27824163, 2016).
autoimmune encephalitis (1 paper, 2013). Inflammation of the brain secondary to an immune response triggered by the body itself. "P2X7-activated DCs have been shown to be crucial for the induction of tumor immunity, the lack of P2X7 signaling decreases the severity of EAE, and oxidized ATP (oxATP), an inhibitor of the ATP receptor P2rx7, ameliorated autoimmune type I diabetes and autoimmune encephalitis in mice." (PMID 23772226, 2013).
breast tumor (1 paper, 2024). "Also, P2RX7 can regulate the expression of the cell adhesion molecule E-calmodulin through the AKT signaling pathway, thereby promoting the growth and migration of breast tumor cells." (PMID 38180750, 2024).
childhood cancer (1 paper, 2025). "Indeed, it would be interesting to add a genetic screening to the clinical guidelines for patients diagnosed with childhood cancer targeting the RARG- rs2229774 risk variant, the SLC28A3-rs7853758 protective variant or the harmful union of the P2RX7-rs208294 and P2RX7-rs3751143 variants." (PMID 40413218, 2025).
colorectal tumor (1 paper, 2024). "It has been shown that overexpression of P2RX7 can promote colorectal tumorigenesis and assess the prognosis of colorectal tumor patients." (PMID 38180750, 2024).
coronary artery stenosis (1 paper, 2023). "The expression of P2RX7 has been found to be upregulated in human carotid atherosclerotic plaques, and this elevation has been correlated to the degree of coronary artery stenosis." (PMID 37649719, 2023).
intrahepatic cholangiocarcinoma (1 paper, 2022). A carcinoma that arises from the intrahepatic bile duct epithelium in any site of the intrahepatic biliary tree. "In intrahepatic cholangiocarcinoma, a mutation in IDH1 (R132C) suggested that the downregulation of P2RX7 was associated with the release of sEVs, further supports that mutations in IDH1 promote the release of sEVs." (PMID 36710884, 2022).
leprosy (1 paper, 2021). Leprosy is a chronic infectious disease affecting primarily the skin and peripheral nervous system. "Allele and genotype distribution of polymorphisms rs1718119 in the P2RX7 gene in patients with leprosy and controls." (PMID 34795692, 2021). "This is the first study to associate the genetic variants c.1513A>C and c.1068G>A of P2RX7 with leprosy." (PMID 34795692, 2021). "In this work, we intend to fill this gap by investigating P2RX7 polymorphisms and P2X7 messenger RNA expression levels (in silico) in Brazilian leprosy patients." (PMID 34795692, 2021). "In addition, we also evaluated the association of two P2RX7 single-nucleotide polymorphisms (c.1513A>C/rs3751143 and c.1068A>G/rs1718119) with leprosy risk." (PMID 34795692, 2021). "Here, we first compare the P2RX7 expression in RNA-seq experiments from 16 leprosy cases and 16 healthy controls to establish the magnitude of allele-specific expression for single-nucleotide polymorphisms of the gene P2RX7 and to determine the level of gene expression in healthy and diseased skin." (PMID 34795692, 2021). "One polymorphism of loss of function and another of gain of function of the P2RX7 gene, associated with susceptibility and protection, respectively, both found here in this study, suggests the involvement of P2X7 in the leprosy immunopathology." (PMID 34795692, 2021). "The expression of P2RX7 was found significantly upregulated at macrophage cells from leprosy patients compared with healthy controls, mainly in macrophages from lepromatous patients." (PMID 34795692, 2021).
ocular toxoplasmosis (1 paper, 2023). Ocular toxoplasmosis is an infection in the eye caused by the parasite, Toxoplasm a gondii. "Therefore, we aimed to investigate the C-terminal region of this gene in ocular toxoplasmosis by studying possibly functional, nonsynonymous polymorphisms within a ~7.2 kb long region around Gln460Arg, the most widely investigated SNP in the P2RX7 gene, including the Ala348Thr (rs1718119) variant." (PMID 37894166, 2023).
vasculitis (1 paper, 2022). "Given that P2RX7 is not essential for the development of GN and vasculitis in rats, this raises questions concerning the importance of IL‐1β." (PMID 35239186, 2022). "Given the upregulation of P2RX7 in renal cortex from animals with experimental GN, it was surprising that the KO rat was not protected from in vivo models of GN and vasculitis." (PMID 35239186, 2022).
tumor (214 papers, 2010 to 2026). "In particular, the ionotropic ATP receptor P2RX7 is known to be associated with GBM tumor formation, and we and others have shown that P2RX7 is expressed and functional in both GL261-AC and GL261-NS cells." (PMID 41400763, 2025). "Further research is needed to clarify the actual role of P2RX7 in tumorigenesis, depending on cancer types, activation pattern, splice variants and tumor microenvironment (TME), such as acidosis, hypoxia and high extracellular ATP (eATP) concentration." (PMID 36803784, 2023). "On the other hand, many reports show an increase of P2RX7 expression in various tumor cell lines and in patients and this increase is linked to tumor growth, as discussed in the previous section." (PMID 37298187, 2023). "This antibody alone attenuates tumor growth, and when combined with the PD-1 antibody, it further slows tumor progression; 50% of mice show complete tumor rejection via a mechanism associated with P2RX7/NLRP3/IL-18 activation in myeloid cells." (PMID 35454832, 2022). "Mechanistically, we observed that the differential expression of the P2RX7B splice variant in immune cells within tumor area correlates with the expression of a less functional P2RX7 and lower leukocytes recruitment into LUAD." (PMID 33510147, 2021). "Loss of the P2rx7 expression in two cell lines derived from 4T1 cells led to a significant delay in primary tumour growth, while the cells demonstrated a slight increase in the proliferation rate compared to the P2rx7+/+ cells." (PMID 32825056, 2020). "In fact, all tumor types listed in The Cancer Genome Atlas were found to have upregulated levels of P2RX7 expression, with sub-type-specific mutation patterns highlighting the significant potential for novel therapeutic approaches in this area." (PMID 30003075, 2018). "Among five CpG loci whose methylation was significantly associated (Q<0.05) with lymph node status, four (two in COL1A2, and one each in LOX and P2RX7) were also associated with tumor size (Q<0.05)." (PMID 20686660, 2010). "Next, we explored the underlying mechanisms by which P2RX7 modulated tumor metabolism." (PMID 36803784, 2023). "If true, expression of P2RX7B will give a growth advantage and explain how P2RX7 expression (likely A and B isoforms) could have been linked to tumor growth and invasiveness in several cancer types 36-39." (PMID 33042257, 2020). "Moreover, attempt to facilitate P2RX7 activation in the field of oncology has been limited by the finding that P2RX7 variants expressed by some tumor cells may sustain their proliferation and metabolic activity." (PMID 33510147, 2021). "In contrast, tumor-associated samples (gene sets 3 and 4) contained upregulated inflammation-related genes (Tnfrsf9, Fasl, Ccr5) and purinergic pathway genes (CD38, P2rx7)." (PMID 41279375, 2025). "Herein, we demonstrate that P2RX7 is highly expressed in tumor tissues from Gem-R PDAC patients and promotes the proliferation and aggressiveness of Gem-resistant PDAC cells." (PMID 41469519, 2025). "Extracellular ATP released by dying tumor cells acts as a "find me" signal, mediating DCs recruitment, activation, and inflammatory responses through binding to P2RX7 purinergic receptors on DCs." (PMID 40104638, 2025). "Then P2RX7 participates in cell proliferation and tumor metastasis by inducing cells to secrete cell cytokines such as interleukin-6." (PMID 41007849, 2025). "To explore the mechanisms by which P2RX7 blockade affects tumor growth via antitumor immunity, we evaluated the infiltration of general CD3+ and cytotoxic CD8+ T lymphocytes." (PMID 38195677, 2024). "After treatment, we found that administration of the P2RX7 antagonist A438079 significantly influenced FOLFOX-induced tumor regression (5D and 5E)." (PMID 38195677, 2024). "We found that OXP led to a significant decrease in tumor growth when administered in combination with the P2RX7 activator BzATP." (PMID 38195677, 2024).
tumor (continued). "Biosynthesis and metabolism are maintained at a high level in tumor cells, which is partially attributed to the key regulator P2RX7." (PMID 36803784, 2023). "Out of 21 ICD-related genes with notably different expressions, seven genes, namely ROCK1, BCL2, TLR2, TLR9, AGER, CASR, and P2RX7, were found to have decreased expression in tumor samples, while the rest were upregulated." (PMID 37932362, 2023). "P2RX7 has immunomodulatory and anti-tumor proprieties and is therefore a therapeutic target for various diseases." (PMID 36600200, 2023). "Studies have shown the ability for transfection of P2RX7 to promote growth, potentially by the expression of factors involved in tumor progression and metastasis." (PMID 37241023, 2023). "Even though P2RX7 has been shown to promote tumor growth when expressed by tumor cells, its expression and activity on immune cells has mostly been associated with antitumor effects by enhancing antitumor immunity." (PMID 37298187, 2023). "Activation of P2RX7 enables HEK293 cells to fulfil increased energy demands for tumor growth through promoting both glycolysis and oxidative respiration via upregulation of the expression of numerous genes related to glucose metabolism." (PMID 36803784, 2023). "Ectonucleotidase CD73 was expressed highly in macrophages, Treg, and CD8+ Teff, while CD39 was prominent in Teff in tumor-bearing p2rx7–/– mice." (PMID 36741002, 2023). "The ATP/P2RX7 axis boosts anti-tumor immune response, as exATP attracts DC precursors to the tumor bed, in the immediacy of dying cells, and promotes their ability to present tumor-associated antigens." (PMID 36741002, 2023). "Even though we and others have shown in vivo that boosting the activation of P2RX7 occurs mostly in immune cells, caution should also be taken with the functionality of the receptor expressed by tumor cells." (PMID 37298187, 2023). "As an indication that the ATP-P2RX7 axis also modulates T cell metabolism, overexpression of P2RX7 confers an intrinsic ability to upregulate aerobic glycolysis and mitochondrial reactive oxygen species (ROS) in fast-growing tumor cell lines." (PMID 36993971, 2023). "Obviously, c-Myc knockdown greatly impaired the ability of P2RX7 to facilitate tumor growth, which was further confirmed by bioluminescence examination." (PMID 36803784, 2023). "In a mammary 4T1 cancer mouse model, P2RX7 expression promoted tumor growth and metastasis and was reversed by P2X7R antagonists." (PMID 36741002, 2023). "Currently, it is known that P2RX7 has a unique impact on the mitochondrial promotion of growth during tumor progression." (PMID 37241023, 2023). "In order to test the role of P2RX7 in tumor growth and lung metastasis, we established an orthotopic OS model with spontaneous metastasis in nude mice by injecting P2RX7 WT and KO MNNG/HOS cells into tibia." (PMID 36803784, 2023). "exATP release drives DC recruitment and activation by P2RX7 ligation, generating adaptive immunity against cancer by tumor-derived antigens and IL-1β secretion." (PMID 36741002, 2023). "Nevertheless, there are also controversial reports that point out the opposite effects of P2RX7, inhibiting tumor development and progression." (PMID 36803784, 2023). "P2X7 stimulation restricted tumor suppression by inducing stress-induced premature senescence (SIPS) in tumor-infiltrating lymphocytes (TIL) and transfer of p2rx7-/- CD8 T cells reduced tumor growth with improved survival in lymphopenic mice." (PMID 36741002, 2023). "We further elucidate that P2RX7 enhances glucose metabolism and tumor growth and metastasis by increasing c-Myc stabilization." (PMID 36803784, 2023). "In this study, we first demonstrated that P2RX7 promotes tumor growth and metastasis through metabolic reprogramming." (PMID 36803784, 2023).
tumor (continued). "Consistent with this later finding, we recently published results showing that a positive allosteric modulator of P2RX7, in combination with immunotherapy, efficiently inhibited tumor growth in transplantable and oncogene-driven lung tumor models." (PMID 35454832, 2022). "Our future goals are to examine the effects of eATPase inhibition and P2RX4 and P2RX7 activation on TNBC models in vivo in the context of an intact tumor microenvironment and functional immune system." (PMID 35515134, 2022). "Despite the finding that P2RX7 expression by immune cells restrains tumor growth, the use of specific P2RX7 antagonists has been promoted to treat cancers on the basis that inhibition of tumor cell proliferation would be more efficient." (PMID 33510147, 2021). "Studies from our group and others have demonstrated that tumor cells upregulate the P2 purinergic receptors P2RY1, P2RY2, P2RX3 and P2RX7 and utilize extracellular ATP to support tumor growth and metastasis." (PMID 33420030, 2021). "Despite its controversial function, P2RX7, a plasma membrane receptor for extracellular ATP that is expressed at a high level by immune and tumor cells, also belongs to the PPI network of ARL11 (score = 0.7)." (PMID 34502169, 2021). "To do so, we use syngeneic immunocompetent tumor mice models and show that activation of P2RX7 improves mice survival." (PMID 33510147, 2021). "P2RX7 expressed by DC has been shown to link innate and adaptive immune responses against dying tumor cells upon chemotherapy-induced ICD and facilitate tumor antigens presentation to T cells." (PMID 33510147, 2021). "For example, released eATP can ligate P2RX7 on dendritic cells to drive its recruitment and activation, which then generate adaptive anticancer immunity by the process of tumor-derived antigens and secretion of interleukin-1β." (PMID 34322664, 2021). "Released ATP induces the recruitment of antigen-presenting cells (APCs), including DCs at the tumor site, by activating the purinergic receptors P2RX7 and P2RY2." (PMID 33919653, 2021). "The two tumor cell lines used in this study express different levels of P2RX7, yet HEI3090 required P2RX7’s expressing immune cells to inhibit tumor growth in both tumor mouse models." (PMID 33510147, 2021). "This receptor participates in tumor growth, differentiation, metabolism, migration invasion, and cell death, so the P2RX7 overexpression is related to poor prognosis in patients." (PMID 34439196, 2021). "In particular, P2RX7 has been reported to act on tumor cell growth, cancer cell metabolism, invasiveness, metastatic spreading, angiogenesis and drug resistance." (PMID 34768902, 2021). "It was demonstrated that ATP released from dying tumor cells as a result of chemotherapy can act on P2X7 purinergic receptors (P2RX7) (most potent activator of the NLRP3 inflammasome) and trigger the activation of the inflammasome." (PMID 33840390, 2021). "Immunohistochemistry (IHC) staining of human GBM tissues have shown that P2RX7 expression is generally higher in tumor than in non-tumor samples and increases with higher grade." (PMID 34067658, 2021). "Loss of function polymorphisms in TLR4 or P2RX7 fail to impact clinical outcome in patients with non-small cell lung cancer, suggesting that tumor biology, chemotherapeutic agent, or both may influence whether tumor cell death is immunogenic, and which cell death pathway is activated." (PMID 32423420, 2020). "We also found that the anti-tumor effect of Arf1 knockdown in wild-type mice was lost in both the DCs-KO and P2RX7-KO mice." (PMID 31924786, 2020). "The knock-down of P2rx7 expression in Crispr#1 and Crispr#2 cells remained stable in the whole duration of the in vivo experiments as well as in primary tumours generated by these cells." (PMID 32825056, 2020). "In this context, the P2RX7/NLRP3 pathway is essential, as the anti-tumor effect of oxaliplatin is lost in mice deficient in these proteins." (PMID 32635472, 2020).